MMP9 (matrix metallopeptidase 9)
Diseases named in the same sentence as MMP9 in open-access papers (continued):
Sharing a sentence is not in itself a finding about the gene and the disease.
cancer (continued). "Snail is a transcription factor that increases MMP-9 expression and triggers an epithelial-mesenchymal transition (EMT); then, carcinoma cells change their morphology, reduce their intercellular and cell-matrix adhesions, and increase their motility." (PMID 23365550, 2013). "Several studies confirmed that high preoperative serum or plasma MMP-2, MMP-9 and mainly TIMP-1 antigen levels are strong prognostic factors for patients with CRC and their determination might be useful for identification of patients with higher risk for cancer recurrence." (PMID 23202950, 2012). "First, both E-selectin and MMP9 have been shown to be involved in the process of trans-endothelial migration (TEM) of leukocytes and cancer cells." (PMID 23190470, 2012). "In cancer, MMPs are involved in angiogenesis by regulating the bioavailability of vascular endothelial growth factor (VEGF) (e.g., MMP-9) and the cleavage of matrix-bound VEGF (MMPs-3, -7, -9)." (PMID 23202950, 2012). "The real-time qPCR confirmed the CCL2, CCL3, CD163, CSF1R, MMP9, HIF1, VEGF-C up-regulation in cancer cells grown as a co-culture with macrophages." (PMID 22353646, 2012). "The migration and invasion of cancer cells requires breakdown of the extracellular matrix (ECM) and basement membrane by proteases such as MMP-2 and MMP-9." (PMID 22962576, 2012). "Degradation of ColIV was closely related to increased MMP-2 and MMP-9 expression; MMP-9 have more important function than MMP-2 during the cancer development." (PMID 23107277, 2012). "Several recent studies demonstrated that high preoperative serum or plasma MMP-2, MMP-9 and TIMP-1 antigen levels are strong predictive factors for poor prognosis in patients with CRC and their determination might be useful for identification of patients with higher risk for cancer recurrence." (PMID 23202950, 2012). "In our experiment, PE downregulated the expression of MMP-2 and MMP-9, and activated TIMP-2, revealing a double strength anti-cancer effect." (PMID 21799674, 2011). "Increased levels of MMP-9 and MMP-2 expression have been correlated with an invasive phenotype of cancer cells." (PMID 21813027, 2011). "The effect of FOXM1 was further confirmed by examining the expressions of known markers in cell migration/invasion, MMP-9 and uPAR, which are in line with the metastatic role of FOXM1 reported in other human cancers." (PMID 21858223, 2011). "Among these enzymes, MMP-2, MMP-9 and urokinase plasminogen activator (u-PA) can directly degrade most components of the ECM and are deeply involved in cancer invasion and metastasis." (PMID 19789215, 2011). "We further observed that 17β-estradiol treatment inhibited PGE2-induced uPA, MMP-9 and cellular motility by suppressing activation of JNK1/2 in human LoVo cancer cells." (PMID 21859479, 2011). "Several lines of evidence have indicated that MMP species such as MMP-2, MMP-7, MMP-9 and MMP-14 (MT1-MMP) have key roles in invasion and metastases of cancer cells." (PMID 22015555, 2011). "In the present study, we observed that JNK1/2 signaling pathway mediated expression of uPA and MMP-9 in response to PGE2, which further contributed to cellular motility of human LoVo cancer cells." (PMID 21859479, 2011). "After administration of inhibitors including LY294002, U0126, SB203580, SP600125 or QNZ, we found that PGE2 treatment up-regulated uPA and MMP-9 expression via JNK1/2 signaling pathway, thus promoting cellular motility in human LoVo cancer cells." (PMID 21859479, 2011). "Gelatin zymography assays indicated that THL dose-dependently inhibited the secretion of MMP-2 and MMP-9 in MDA-MB-231, H1299, PC-3 and CT-26 cancer cells." (PMID 20429953, 2010). "It is well established that invasiveness and the ability of cancer cells to migrate in vitro and in vivo is mediated by various metalloproteases (including MMP-2 and MMP-9) and urokinase plasminogen system (uPA, uPAR and PAI-1)." (PMID 20404912, 2010).
cancer (continued). "This was especially true for MMP-9, MMP-3 and CycD1, the concentrations of which in cancer patients were lower by 65 (P<0.000003), 40 (P<0.0007) and 34% (P<0.0001), respectively." (PMID 20216542, 2010). "THL inhibited the migration and invasion ability of various cancer cells in vitro, decreased the secretion of MMP-2, MMP-9, and uPA and the activity of ERK1/2 in cancer cells, and suppressed pulmonary metastasis of CT-26 cancer cells in syngenic mice." (PMID 20429953, 2010). "Gelatin zymography showed bands corresponding in size to MMP-2, MMP-3, MMP-9, and MMP-10 enzymes in each of the 24 cancer cases." (PMID 20920372, 2010). "Three types of cancers are covered by 22 2-gene combinations, with MMP11+RRM2 and MMP7+MMP9 representing the top 2-gene markers with at least 75% classification accuracy." (PMID 21060876, 2010). "Another study showed that berberine suppresses invasion of cancer cells through different signalling pathways resulting in inhibition of MMP-2 and MMP-9." (PMID 20652055, 2010). "The lower the target temperature of RFA was, the higher was the expression of MMP-9, VEGF and PCNA in residual hepatic VX2 carcinoma tissues." (PMID 20667141, 2010). "MMP-9 and LDH have been measured quativavely in saliva of OSCC cancer patients whereas salivary carbonyls were studied by a western gel only." (PMID 19789535, 2009). "Western blot analysis demonstrated elevated protein levels of MMP-9, DJ-1 and A1BG in cancerous pancreatic juice compared with cancer-free pancreatic juice, which is consistent with our proteomic findings." (PMID 18706098, 2008). "Particular MMPs (including MMP-2, MMP-9 and MMP-14) are involved in key events in cancer cells, including proliferation, apoptosis and angiogenesis." (PMID 17894888, 2007). "Constitutive expression and activity of MMPs increases the invasiveness of various types of cancer cells, and we have determined characterized the expression of MMP-2, MMP-9 and MMP-14 as well as TIMP-1 and TIMP-2 mRNA in EN-1078D cells, using RT-PCR." (PMID 17894888, 2007). "Carcinomas contained significantly higher MMP-2 and MMP-9 levels in antigen as well as activity than adjacent normal tissue." (PMID 16538217, 2006). "Two of the best studied MMP's in angiogenesis and cancer are MMP-2 and MMP-9 (gelatinase-A and -B), which amongst other molecules degrade collagen IV, one of the major components of the basement membrane." (PMID 12189553, 2002). "MMP-9 (92 kDa gelatinase) and MMP-11 (stromelysin 3) were most consistently expressed by carcinomas." (PMID 8645587, 1996). "Matrix metalloproteinase 9 (MMP-9) plays a critical role in the proteolytic degradation of extracellular matrix components and can be released within extracellular vesicles by different cancer cell types." (PMID 40485730, 2025). "Modification of cancer biomarkers, such as decreased PCNA and Ki-67, increased Bax/Bcl-2 ratio, increased cleaved caspase-3, decreased VEGF and CD31, and decreased matrix metalloproteinases, especially MMP-2 and MMP-9, were also observed." (PMID 41322296, 2025). "K8/18 depletion leads to hyperactivation of the PI3K/AKT/ nuclear factor kappa B (NF-κB) pathway and increased expression of matrix metalloproteinase 2 (MMP2) and matrix metalloproteinase 9 (MMP9), which prompts the tight junction protein claudin-1 to assume an active role in cancer progression." (PMID 40229242, 2025). "MMP9, plays a crucial role in extracellular matrix (ECM) remodeling, which is essential for various physiological and pathological processes, including wound healing, inflammation, and cancer metastasis." (PMID 41259376, 2025). "On the contrary, other genes, such as VIM and MMP9, seemed completely nonspecific and not correlated to an increase in cancer cell aggressiveness." (PMID 40332096, 2025). "In addition, by decreasing matrix metalloproteinase-9 (MMP-9) activity, RA successfully prevented the invasion and migration of cancer cells." (PMID 40427522, 2025).
cancer (continued). "Additionally, cyclooxygenase-2 (COX-2) in TAMs induces MMP-9 expression, further promoting EMT in cancer cells." (PMID 40134439, 2025). "MMP-9 is the most studied MMP, and it plays a pivotal role in cancer cell invasion and metastasis." (PMID 40017656, 2025). "Meanwhile, we also identified novel cancer drivers, such as PXDNL, YWHAZ and MMP9." (PMID 40478912, 2025). "Pomegranate peel extract (rich in gallic acid, ellagic acid, protocatechuic acid, rutin) showed promising effects in a rat model of colorectal cancer and might act upon cancer stem cells through decreased EMT and MMP-9 inhibition." (PMID 39859345, 2025). "Malignant tumors are well-documented to stimulate angiogenesis in adjacent tissues through mechanisms involving vascular endothelial growth factor (VEGF) and matrix metalloproteinase-9 (MMP-9)." (PMID 40026939, 2025). "However, the upregulation of miR-34a culminated in the increased apoptosis of cancer cells while downregulating MMP-2 and MMP-9 expression, inhibiting invasiveness and migration of cancer cells." (PMID 40575155, 2025). "In addition, we analyzed the protein levels of IL6 and markers of TAMs, including matrix metalloproteinase 9 (MMP9) and arginase 1 (Arg1), in HCC cancer tissues and adjacent tissues." (PMID 39744421, 2025). "Various cancers show notably increased MMP gene expression and activity, particularly MMP9." (PMID 40699769, 2025). "Under hypoxic conditions, HIF1α is stabilized and activated, leading to the upregulation of key factors, including vascular endothelial growth factor (VEGF), which drives angiogenesis, matrix metallopeptidase 9 (MMP9), and MMP7, which enhance cancer invasion, and EMT-related genes." (PMID 39996805, 2025). "Xanthohumol (Xn), a phenolic compound rich in hops, wine, and beer, could inhibit cancer progression by blocking MMP-2 and MMP-9 activity." (PMID 40563423, 2025). "MMP-9, a gelatinase capable of degrading major ECM components including type IV collagen, plays a critical role in the epithelial–mesenchymal transition (EMT) of cancer cells." (PMID 40284474, 2025). "However, research in this area is still in early stages, targeting MMP9, SPARC and ITGA5 in OSF has the potential to prevent altered ECM remodelling and its contribution to both fibrosis and its progression to cancer." (PMID 39865173, 2025). "• Exertion of anticancer effects through 3 major pathways: apoptosis (BIRC3, BIRC5, caspase-8, caspase-9, and PARP1), transcriptional dysregulation in cancer (CDKN1A, CDKN1B, MMP9, MYC, JUN, and RELA), and cancer progression (caspase-3, CCND1, CTNNB1, VEGFA, and Wnt-1)." (PMID 39181121, 2025). "It has been shown to inhibit cancer growth through various mechanisms, including apoptosis induction via caspase activation and Bcl2 inhibition, PI3K/AKT/mTOR and MAPK/ERK pathway modulation in addition to angiogenesis inhibition via VEGF and MMP9 inhibition." (PMID 40396612, 2025). "Furthermore, MMP-9 induces endothelial cell migration and activates the angiogenic switch via increased vascular endothelial growth factor (VEGF) release during cancer development." (PMID 40869267, 2025). "However, in malignant tumors, activated MMP-2 and MMP-9 degrade the matrix, promoting cancer cell infiltration." (PMID 40607416, 2025). "Similarly, phorbol ester-treated THP-1 cells enhanced cancer cell invasion and angiogenesis via COX-2-dependent MMP-9, VEGF-A, and bFGF release." (PMID 40649978, 2025). "The significant upregulation of MMP3 and MMP9 genes in VCP-overexpressing hCMEC/D3 cells suggests a potential role for VCP in modulating extracellular matrix dynamics and tissue remodeling processes, crucial for angiogenesis and cancer metastasis." (PMID 39802400, 2025). "As speculated, in two TNBC cell lines, SAMD5 overexpression significantly inhibited cell viability, colony formation, and cell invasion, as well as cancer biomarker levels, including Ki67, MMP2, and MMP9." (PMID 39524172, 2024).
cancer (continued). "Although we have shown that SNPs in MMP2 and MMP9 are associated with increased risks of UTUC and metastasis, the effect of individual SNPs on cancer risks and outcomes is modest and not clinically applicable." (PMID 39063556, 2024). "Cancer stem cells from different tumors show IL-1- and TNF receptor superfamily (TNFSF)-dependent NF-κB activation that determines the transcription of EMT genes, such as NANOG, SNAIL, SLUG, ZEB1, ZEB2, and TWIST, as well MMP-2 and MMP-9." (PMID 39519020, 2024). "Furthermore, cancer progression and metastasis can be accelerated by the impairment of MMPs, especially MMP2 and MMP9, which are a subgroup of Zn-dependent MMPs." (PMID 38732186, 2024). "There is no debate that the increased expression of Neu-1 and MMP-9 has an impact on cancer progression through the modulation of inflammation, tumorigenesis, and insulin receptor signaling." (PMID 38534324, 2024). "Additionally, it has been proved that GSs suppress the proliferation of cancers via transforming MMP-2 and MMP-9." (PMID 38672151, 2024). "MMPs, particularly MMP-9 and MMP-2, are instrumental in cancer-related processes." (PMID 38693104, 2024). "MMP9 upregulation occurs via targeting of AP-1 transcription factors by the p38 MAPK and JNK signalling pathways, which many studies have shown contribute to cancer development and progression." (PMID 38906916, 2024). "MMP-9 siRNA was loaded onto the poly(L-lysine) dendrons and the particles subsequently induced expression of MMP-9 in MCF-7 cells, yielding significant apoptosis of these cancer cells." (PMID 38634994, 2024). "Decreased the mobility of MDA-MB-231 cancer cells and the expression of MMP-2 and MMP-9 genes." (PMID 39712006, 2024). "They revealed that this anti-cancer effect may be attributed to the direct inhibition of NOTCH3 signaling and indirect interactions with MMP-9 expression." (PMID 39858430, 2024). "Molecularly, RBP4 induced the expression of cancer progression factors MMP2 and MMP9." (PMID 38913193, 2024). "One downregulated protein, matrix metalloproteinase-9 (MMP9), and two upregulated proteins (NADPH: quinone oxidoreductase-1 (NQO1) and Sodium/potassium ATPase (Na+/K+-ATPase)) were correlated with a suppression in the proliferation and migration of cancer." (PMID 38732643, 2024). "In this review, we first briefly address MMPs and their critical roles in human health and cancer progression; then, we address natural products from marine organisms and plants that could regulate MMP-2 and MMP-9 expression levels and activities." (PMID 38672151, 2024). "Furthermore, the transcriptional downregulation of Mortalin was connected to a reduction in N-cadherin, fibronectin, MMP3, MMP7, MMP9, MMP2, vimentin, and hnRNP-K (key proteins involved in the cell migration and metastatic characteristics of cancer cells." (PMID 39456564, 2024). "Both E-cadherin, a key epithelial cell marker and MMP9, one of most widely studied matrix metalloproteinases (MMPs), have been proposed to induce EMT and play a crucial role in the development of malignant tumors." (PMID 39030572, 2024). "Nevertheless, the differential expression of EGFR and VEGFc, in addition to MMP9 and CXCL5, differentially packaging into IRF5-low versus IRF5-high EVs across two cancer types provide insight into the mechanisms by which IRF5 contributes to protection from PMN formation." (PMID 38969706, 2024). "Based on the benefits of both high sensitivity and excellent selectivity, this method was used to distinguish the difference in MMP-9 levels between normal and cancer cells as well as the expression of MMP-9 from cancer cells with different degrees of metastasis." (PMID 38240894, 2024). "Previous studies suggested that STAT3 activation play a crucial role in the cancer invasion and metastasis by modulating the MMPs expression.Our findings revealed that the expression level of MMP2 and MMP9 was remarkably reduced in MCF-7 cells treated with NAR and DOX." (PMID 38310190, 2024).
cancer (continued). "Although the epigenetic regulation of NGAL and MMP-9 in cancer was widely investigated, no data on the role of methDNA in the regulation of SLC22A17 in CM are reported in the literature." (PMID 39358721, 2024). "Similarly, other polyphenolic compounds, such as curcumin, demonstrate broad-spectrum anti-cancer properties, including inhibition of MMP-2 and MMP-9." (PMID 39858430, 2024). "In addition, the genes coregulated by ZBTB11 and SET, such as MMP9 and SPARC, have been well validated to participate in the regulation of cancer cell migration and invasion." (PMID 38355937, 2024). "MMP9 and SCGN not only played regulatory roles in ccRCC, they had also shown value in pan-cancer." (PMID 38375034, 2024). "MMP9’s (Matrix Metalloproteinase 9) key involvement in ECM (Extracellular Matrix) remodeling highlights its significant correlation with the pathogenesis and progression of cancer at every stage." (PMID 38782818, 2024). "The present data on ACE2 siRNA transfection demonstrated the downregulation by ACE2 of HIF1α, MMP9 and β catenin in A549 cells, suggesting that the interaction between ACE2 and HIF1α and other cancer-promoting genes could differ depending on the cancer type." (PMID 39273283, 2024). "In addition, the results evidenced that c-FLIP promotes the motility of cancer cells by activating ROCK, FAK, and ERK, and increasing the expression of MMP-9." (PMID 38339421, 2024). "In this regard, quercetin has been shown to impact it by downregulating the expression of matrix metalloproteinases (MMPs) such as MMP9 and MMP2, which play a significant role in the degradation of the extracellular matrix, thereby inhibiting the migration and invasive potential of cancer cells." (PMID 39200268, 2024). "It appears that polyphenols may be valuable options for the chemoprevention and treatment of cancer via the inhibition of MMP-2 and MMP-9 and the suppression of signaling pathways regulating their expression and activity." (PMID 39335164, 2024). "MMP9 is regulated by several key signaling pathways, including JAK2/STAT3, Wnt/β-catenin, ERK, and PI3K/AKT, each contributing to its upregulation and the progression of cancer." (PMID 39664453, 2024). "Furthermore, NF-κB regulates cancer cell invasion by controlling the expression of adhesion molecules such as fibronectin and vitronectin, which influence MMP-2 and MMP-9 activity." (PMID 39684484, 2024). "MMP9 upregulation occurs via the p38 MAPK and JNK signalling pathways that targets the AP-1 transcription factor; many studies have shown that this pathway contributes to cancer development and progression." (PMID 38906916, 2024). "Follow-up pharmacodynamic experiments demonstrated that EJ significantly inhibited metastasis of cancer cells both in vitro and in vivo, and that the protein levels of STAT3, MMP-2, and MMP-9 could be dose-dependently reduced by EJ." (PMID 37049904, 2023). "IL-17A mediates cancer cell invasiveness and metastasis via MMP-2, MMP-9, and MMP-13." (PMID 36993955, 2023). "They include MMP9, VEGF, and PDGF, which can promote both cancer cell proliferation and metastasis." (PMID 36728187, 2023). "In normal gingival cells, oral dysplasia, and cancer patient specimens, arecoline has been demonstrated to induce the expression of MMP-9, but not in keratinocytes and OSSC cells." (PMID 37190117, 2023). "Moreover, p38/NF-kB-mediated transcription products such as TNF-α, MMPs (MMP-2 and MMP-9), VEGF (also called VEGF-A and located at chromosome 6p12), VEGF-C, and PGE1/2 facilitate the invasion and metastasis of cancer (34, 41,)." (PMID 36993955, 2023). "Although these are not comparative studies of cancer patients, they indicate that increase in MMP-9 is detectable with similar efficiency at both mRNA and protein levels." (PMID 36765669, 2023). "Altogether, these results suggest that 5α-reductase inhibition may decrease cancer cell progression and migration via p21, Bcl-2, MMP2, MMP9, NF-κB, and GSK3β signaling pathways." (PMID 36800968, 2023).